IL32 (interleukin 32)
Diseases named in the same sentence as IL32 in open-access papers (continued):
Sharing a sentence is not in itself a finding about the gene and the disease.
melanoma (continued). "This revealed a significant positive correlation of IL-32 gene expression to the mature DC signature not only in melanoma, but in all 33 available TCGA cohorts." (PMID 32841222, 2020). "Here, we demonstrate that IL-32 expression in human melanoma positively correlates with overall survival, response to ICB, and an immune-inflamed tumor microenvironment (TME) enriched in mature DC, M1 macrophages, and CD8+ T cells." (PMID 32841222, 2020). "Treatment of B16F10 murine melanomas with IL-32 increased the frequencies of activated, tumor-specific CD8+ T cells, leading to the induction of systemic tumor immunity." (PMID 32841222, 2020). "To assess the cellular source of IL-32 within the tumor, we examined previously annotated single-cell RNA-Seq data from patients with melanoma." (PMID 32841222, 2020). "We found that TNFα and IFNγ, which promote a dedifferentiated melanoma phenotype, also induce IL32 expression in non-IL32 expressing melanoma cell lines by impacting activity at the promoter level." (PMID 30953519, 2019). "Immunohistochemical staining of IL32 in melanoma tissues, pulled from The Human Protein Atlas, indicates a range of expression within tumor samples." (PMID 30953519, 2019). "A significant proportion of established human melanoma cell lines express IL32, with its expression being highly correlated with a dedifferentiation genetic signature (high AXL/low MITF)." (PMID 30953519, 2019). "Given the impact of proinflammatory cytokines on IL32 expression, we investigated the IL32 expression in immunologically rich melanoma tumors using RNA sequencing data available in the TCGA dataset." (PMID 30953519, 2019). "We also evaluated the impact of proinflammatory molecules TNFα and IFNγ on IL32 expression and dedifferentiation in melanoma cell lines in vitro." (PMID 30953519, 2019). "We observed strong Pearson correlation coefficients between IL32 expression, found within the melanoma tumor and the surrounding microenvironment, and genes related to immune cell infiltration, such as CD3E (0.94), CD8A (0.89), IFNγ (0.75), and GZMB (0.86)." (PMID 30953519, 2019). "We selected these three melanoma cell lines to observe the parallel impact of TNFα and IFNγ on IL32 and the melanoma differentiation state because they exhibited a low AXL/high MITF differentiated genetic signature." (PMID 30953519, 2019). "Others reported that IL32 isoforms alpha and gamma were highly enriched in PD-L1 expressing melanoma specimens." (PMID 30953519, 2019). "We characterized the transcriptional regulation of IL32 in human melanoma, both in constitutive and cytokine-induced cells." (PMID 30953519, 2019). "Expression of IL32 in human melanoma can be induced by TNFα or IFNγ and correlates with a treatment-resistant dedifferentiated genetic signature." (PMID 30953519, 2019). "Together, this suggests that IL32 is among several hundred melanoma genes whose expression is affected by exposure to these proinflammatory cytokines." (PMID 30953519, 2019). "Transcripts for IFN-g, IL-10 and IL-32 g were over-expressed in PD-L1+ compared to PD-L1(−) melanoma biopsies; in vitro, IL-10 and IL-32 g induced PD-L1 expression on Monos but not on melanoma cells." (PMID 31730010, 2019). "In an analysis of the RNA transcripts from 53 established melanoma lines, a significant proportion express IL32 isoforms." (PMID 30953519, 2019). "Non IL32-expressing differentiated melanoma cell lines exposed to TNFα or IFNγ can be induced to express the three predominant isoforms (α, β, γ) of IL32." (PMID 30953519, 2019). "The significant contribution of IL-18 during melanoma progression enabled us to investigate the role of IL-32 in melanoma migration in this study." (PMID 27589563, 2016). "IL32 has been shown to support tumor suppression in transgenic mice inoculated with melanoma and colon cancer cells and up-regulated in lung adenocarcinomas where it is considered a potential clinical target." (PMID 25100201, 2014).
melanoma (continued). "Adipocytes in obese patients with melanoma release high amounts of pro-inflammatory cytokines and growth factors (IL-6, IL-32 or TNF-α) and molecules involved in the angiogenesis enhancement (OPN—osteopontin, chemerin, apelin and PAI-1) that modulate melanoma proliferation." (PMID 40136652, 2025). "IL-32 has been mooted as a biomarker in skin conditions including atopic dermatitis and melanoma and ascribed a proinflammatory, host-protective role in tuberculosis, leishmaniasis, colitis, and arthritis on the basis of the use of human IL32–transgenic (huIL32-transgenic) mouse models." (PMID 40371647, 2025). "The effect of IL-32 on melanoma cells has also been studied." (PMID 37727785, 2023). "Treatment of murine melanoma with IL-32 improved dendritic cell function and triggered M1 polarization as well as CCL5 release in macrophages, resulting in CCR5-mediated CD8 + T cell infiltration into the tumor microenvironment and the eradication of cancer cells." (PMID 33827575, 2021). "IL-32 also correlates with response to anti-PD-1 treatment in patients with melanoma." (PMID 33827575, 2021). "Therefore, a systematic analysis of the correlation between IL32 expression and patient survival is essential to comprehensively understand the role of IL-32 in melanoma patients." (PMID 34682815, 2021). "Hence, we investigated the therapeutic potential of intratumoral IL-32γ administration in murine cancer models, while simultaneously assessing the immunological correlates and prognostic value of high IL-32 expression in human melanoma." (PMID 32841222, 2020). "Overall, we revealed a detailed mechanism of action of IL-32 in melanoma." (PMID 32841222, 2020). "Therefore, IL-32 is a potential prognostic biomarker in melanoma; however, this finding requires further validation in a prospective study." (PMID 32841222, 2020). "Furthermore, increased baseline IL-32 gene expression was associated with response to nivolumab and pembrolizumab in 2 independent cohorts of patients with melanoma, implying that IL-32 is a predictive biomarker for anti–PD-1 therapy." (PMID 32841222, 2020). "Gene expression scatterplots of MITF and TYR vs. IL32 show that melanoma cells with high IL32 expression are typically dedifferentiated, whereas differentiated melanoma are associated with absent or lower levels of IL32." (PMID 30953519, 2019). "It is plausible, then, that IL32 is expanded within the microenvironment as a byproduct of the feedback loop between the anti-tumor inflammatory response (marked by TNFα and IFNγ) and dedifferentiation of melanoma." (PMID 30953519, 2019). "However, it is notable that IL32 levels in melanoma are low relative to other tumor cell lines represented in the NCI-60 Cancer Cell Line database or the Cancer Cell Line Encyclopedia (respectively)." (PMID 30953519, 2019). "IL32 from melanoma cells may influence non-melanoma cells in the tumor microenvironment, such as myeloid cells, which can play both pro- and anti-tumor roles depending on their phenotypic state." (PMID 30953519, 2019). "Across this dataset, IL32 expression was detectable in a majority of the melanoma cell lines." (PMID 30953519, 2019). "We sought to better understand the biology of IL32 in human melanoma." (PMID 30953519, 2019). "Given the impact of TNFα and IFNγ on IL32 expression in melanoma cell lines, we investigated the expression of IL32 in the chemokine-rich melanoma tumor microenvironment using RNA sequencing data from tumor biopsies as part of The Cancer Genome Atlas (TCGA) dataset." (PMID 30953519, 2019). "IL32 was shown to suppress hepatocellular cancers, melanoma and colon cancers." (PMID 25100201, 2014). "Furthermore, IL-32 was detected in most melanoma cell lines." (PMID 34068679, 2021). "In addition, our data suggest that IL-32 gene expression could delineate patients with melanoma who respond to nivolumab or pembrolizumab, highlighting its potential use as a predictive biomarker for response to anti–PD-1 therapy." (PMID 32841222, 2020).
melanoma (continued). "Furthermore, IL-32–matured BMDC displayed significantly elevated mRNA levels of DC maturation markers and T cell–recruiting chemokines, similar to the gene signature associated with IL-32hi human melanomas." (PMID 32841222, 2020). "However, the role of IL32 in human melanoma cells is less well understood." (PMID 30953519, 2019). "A smaller tissue from patient ID 9561, collected in 2008, had four clusters, including melanoma (PMEL, TYRP1), immune cells (TMSB4X, IL32), keratinocytes (KRT10, KRT1, DSG1), and fibroblast areas (COL1A2, COL1A1, DCN)." (PMID 39846232, 2025). "(CD52, CCL5, and IL32), and was resemble with a group of dysfunctional CD8 T cells recently identified in melanoma, esophageal squamous cell cancer and liver cancer." (PMID 35812401, 2022). "Overall, in this study, IL32 expression controlled activated NK cell infiltration in SKCM and improved the prognosis of melanoma patients." (PMID 34682815, 2021). "IL-32 potentiates the effects of ICB in mice and is predictive for response to anti–PD-1 therapy in patients with melanoma." (PMID 32841222, 2020). "We treated established human melanoma cell lines (D10, SK-Mel-37) and multiple FACS-purified immune cell subsets from healthy donor PBMC with IL-32." (PMID 32841222, 2020). "We observed a correlation between IL32 expression in melanoma tumor biopsies with a high AXL/low MITF drug-resistant signature, consistent with data from melanoma cell lines." (PMID 30953519, 2019). "(A-B) Scatterplot of log2 FPKM expression values between IL32 and select immune genes (A) or between the ratio of AXL and MITF log2 FPKM expression values (B) in the melanoma TCGA dataset (n = 479)." (PMID 30953519, 2019). "Interleukin 32 (IL32) is produced by T cells, NK cells and monocytes/macrophages, but also by a subset of melanoma cells." (PMID 30953519, 2019). "STAT1 and IL-32 signaling mediates immunoresponse upon TLR2/6 agonists and IFN-gamma treatment in melanoma." (PMID 31024232, 2019). "We also observed a correlation between IL32 expression, derived from tumor cells and the surrounding microenvironment, and a high AXL/low MITF gene signature, as in the melanoma cell lines." (PMID 30953519, 2019). "Further dissection of cluster 1 induced in IL-32–treated tumors showed significantly increased protein levels of the CCR5-binding chemokines CCL3, CCL4, CCL5, and CXCL2, corroborating the observations in IL-32hi human melanoma." (PMID 32841222, 2020). "IL-32 treatment reprograms DC and macrophages to induce CD8+ T cell infiltration, thereby promoting tumor immunity and response to immunotherapy in murine models of melanoma." (PMID 32841222, 2020). "IL32 mRNA levels were significantly higher in anti–PD-1 treatment–responding patients with melanoma or patients with no disease recurrence compared with nonresponders or patients with recurrent disease in 2 independent cohorts." (PMID 32841222, 2020). "PCA revealed an altered gene expression profile upon IL-32 treatment in monocytes but not in lymphocytes or melanoma cell lines." (PMID 32841222, 2020). "Therefore, we examined the correlation between IL-32 gene expression and the DC marker CD11c (also known as ITGAX) as well as the costimulatory molecules CD40, CD80, and CD86 in melanoma samples from The Cancer Genome Atlas (TCGA)." (PMID 32841222, 2020). "Due to our results showing that IL-32 enhanced intratumoral T cell infiltration, we investigated the capacity of IL-32 to induce responsiveness in non-ICB–responding melanomas." (PMID 32841222, 2020). "The remarkable advances in melanoma immunotherapy occasioned by the development of CTLA-4 and PD-1/PDL1 checkpoint inhibition underscores the importance of understanding potential contributions of melanoma-elaborated cytokines such as IL32." (PMID 30953519, 2019).
melanoma (continued). "Moreover, given the ability of IL-32 to induce a T cell–inflamed TME, it potentiated the response to anti–PD-1 therapy and strongly correlated with response to pembrolizumab and nivolumab in patients with melanoma." (PMID 32841222, 2020). "Additionally, we found a positive correlation between IL-32 and M1 macrophages concomitant with a negative correlation to M0 macrophages in melanoma, suggesting that IL-32 induces both cross-presentation in DC and M1 polarization in macrophages." (PMID 32841222, 2020). "In comparing IL32 expressing and non-expressing melanoma cell lines, we observed that IL32 expression in melanoma cell lines correlates with a high AXL/low MITF ratio, a genetic signature which has been reported to be associated with a treatment-resistant, dedifferentiation “invasive” phenotype." (PMID 30953519, 2019). "Expression of IL32 in human melanoma can be transcriptionally regulated in the context of a proinflammatory tumor microenvironment with either induced or constitutive IL32 expression strongly, but not invariably, correlating with a dedifferentiated genetic signature." (PMID 30953519, 2019). "We therefore conjecture that this long-range enhancer may not play a role in melanoma IL32 transcription." (PMID 30953519, 2019). "IL32 expression in a subset of melanoma cell lines was confirmed by real time PCR (data not shown)." (PMID 30953519, 2019). "Furthermore, we detected no direct cytotoxicity of IL-32 to human and mouse melanoma cells." (PMID 32841222, 2020). "Furthermore, enforced expression of recombinant IL32α, -β, or -γ in M397 did not impact expression of melanoma differentiation genes MITF, AXL, NGFR or MLANA, strongly suggesting that IL32 is not a causal or upstream event in the melanoma dedifferentiation process." (PMID 30953519, 2019).
viral infection (21 papers, 2008 to 2026). "IL-32 is associated with inflammation, virus infections and cancer by participating in multifaceted regulation process such as cancer cell growth inhibition, cell apoptosis regulation, accentuation of inflammation, and angiogenesis." (PMID 33097029, 2020). "The decline in plasma IL-32 levels observed in SARS-CoV-2 infection contrasts with findings in other viral infections." (PMID 40149726, 2025). "Background/Objectives: Interleukin-32 (IL-32) is a pro-inflammatory cytokine primarily produced by immune cells and involved in bacterial and viral infections." (PMID 40149726, 2025). "IL-32 can be expressed by innate immune cells but in cases of viral infection, autoimmunity, and cancer the predominant IL-32 source are T cells." (PMID 39211051, 2024). "While IL-32 induction is beneficial for the control of pathogens, it seems to suppress immune responses at later stages of persistent viral infection, suggesting an ambiguous role in immune regulation." (PMID 39211051, 2024). "IL-32 is involved in various cell functions such as apoptosis, differentiation, viral infection, and modulation of inflammatory cytokines, indicating that it is a cytokine that plays key roles in several diseases." (PMID 37228610, 2023). "The pro-inflammatory monocytes also highly expressed THBS1, PRS20, and IL32 genes, which are involved in viral infection, immune activation, and pro-inflammatory responses." (PMID 36626090, 2023). "Interleukin-32 (IL-32), first reported in 2005, and its isoforms have been the subject of numerous studies investigating their functions in virus infection, cancer, and inflammation." (PMID 37228610, 2023). "Regarding viral infections, an antiviral function of IL-32 has been demonstrated in herpes simplex virus (HSV) infection, where CD8+ T cells expressed IL32 at the dermal-epidermal junction of human genital skin biopsies." (PMID 37727785, 2023). "IL-32, as a proinflammatory cytokine, has been extensively studied, and the mechanisms of action and functions of IL-32 during bacterial and viral infection as well as in cancer have been reviewed." (PMID 30426023, 2018). "Our results reveal that TRIF-dependent RIP-1 and TRAFs activation by TLR3 is critical for IL-32-mediated pro-inflammatory cytokines production in ocular mucous surfaces after viral infection." (PMID 25754842, 2015). "The activation of IFN-λ1 endows IL-32 with extensive antiviral properties, which explains the key role of IL-32 in the viral infection response from yet another perspective." (PMID 26087456, 2015). "In conclusion, sIL-6R acts as an upstream regulatory factor for IL-32 during viral infection and promotes IL-6 production via IL-32, while IL-32 feedback inhibits the IAV-induced sIL-6R expression." (PMID 26087456, 2015). "Because IL-32 plays a key role in the inflammatory response against virus infection, developing a therapeutic strategy that targets IL-32 should be an important research field." (PMID 26087456, 2015). "It was also reported that IL-32 protected against Mycobacterium tuberculosis infection, and viral infection in differentiated THP-1 human macrophages." (PMID 26497686, 2015). "This raises the question of whether systemic IL-32 plays a role in viral infections and disease severity in COVID-19." (PMID 40149726, 2025). "Furthermore, elevated IL-32 levels play important roles in viral infections such as human papillomavirus (HPV), hepatitis C virus (HCV), hepatitis B virus (HBV), Epstein bar virus (EBV), and human immunodeficiency virus (HIV) infections." (PMID 34712431, 2021). "Besides virus infection, IL-32 is involved in inflammatory diseases such as ulcerative colitis, vasculitis, rheumatoid arthritis, and Crohn’s disease." (PMID 26087456, 2015). "The induction of IL-6, mediated by IL-32, is crucial for the host response against viral infection." (PMID 26087456, 2015). "In recent studies, IL-32 has also been found to be regulated during viral infections." (PMID 23402302, 2013).
viral infection (continued). "Recent reports have highlighted that IL-32 is regulated during viral infection in humans." (PMID 23402302, 2013). "Also against viral infections IL-32 plays a role in defence mechanisms." (PMID 24884781, 2014). "IL-32 activates the leukocyte surface protease PR3, which in turn triggers the G-protein-coupled receptor PAR2 and is known to be important in viral infections." (PMID 36045343, 2022). "Viral infections, including IAV infection, increased IL-32 and inducible NO synthase (iNOS) expression." (PMID 26087456, 2015). "Viral infection resulted in 2.7-fold increase in PGE2 synthesis and 58.2% increase in IL-32 production." (PMID 18414668, 2008). "Furthermore, since COX-2 and IL-32 are obligatory mediators of inflammation, the question arises as to whether there is an interaction between the two proteins or they act as independent effectors of host inflammatory response to viral infection." (PMID 18414668, 2008). "Given that a similar reduction was observed in patients with sepsis, it is plausible that disease severity, rather than the viral infection itself, contributes to the decrease in IL-32 levels." (PMID 40149726, 2025). "Results showed that poly(IC), poly(IC)+IFN-γ, and NS1 are the most important factors in the induction of either COX-2 or IL-32 promoter activities, which means dsRNA and NS1 are the key viral components involved in IV-triggered COX-2 and IL-32 expression during viral infection." (PMID 18414668, 2008). "However, IL-32 levels were comparable between the 28 patients with severe COVID-19 and critically ill patients without this viral infection." (PMID 40149726, 2025). "Many studies suggest that this miRNA might be involved in regulating both host and viral gene expression during viral infection to establish and maintain latency through targeting genes, such as MICB, immediate-early (IE) gene products, Toll-Like Receptor (TLR), and Interleukin-32 (IL-32)." (PMID 36591247, 2022).